INS (insulin)
Diseases named in the same sentence as INS in open-access papers (continued):
Sharing a sentence is not in itself a finding about the gene and the disease.
dementia (continued). "The development of multi-target drugs for dementia treatment aligns with the concept of repositioning anti-diabetic drugs for dementia, as the insulin/IGF-1 signaling pathway has been implicated in the majority of dementia subtypes." (PMID 37511207, 2023). "Previous studies have found insulin use increased the risk of all-cause dementia, while its association with dementia subtypes was unclear." (PMID 36804018, 2023). "In contrast, sulfonylureas and insulin were reported to increase the risk of dementia and impaired cognitive function." (PMID 37113972, 2023). "As a result, changes in insulin signaling in the hippocampus can affect molecular mechanisms underlying synaptic plasticity and increase the risk of neurodegeneration and dementia." (PMID 37025701, 2023). "Insulin use was linked to 1.5- and 1.9-times higher risk of all-cause dementia and VD, respectively." (PMID 36804018, 2023). "Taken together, these findings support the idea that genetic variants differentially associated with the two extremes of the insulin spectrum imply the existence of different disease mechanisms for cognitive impairment and dementia." (PMID 37420130, 2023). "A meta-analysis also revealed that patients with T2DM under treatment with insulin presented the lowest risk of dementia compared with other antidiabetic drugs." (PMID 36909158, 2023). "Is cessation of metformin therapy associated with dementia incidence, and is the association mediated by hemoglobin A1c (HbA1c) level or insulin use?" (PMID 37878309, 2023). "The evidence for each of these underlying mechanisms and the link between DM2 and dementia will be examined, with an emphasis on the function of insulin." (PMID 37868425, 2023). "In the specific case of early stage dementia, it is also effective in ameliorating the therapeutic action of insulin, even though it causes a parallel and undesirable hypoglycemic effect." (PMID 37371113, 2023). "Neuroinflammation is also observed due to plaque and tangle formation, oxidative stress markers, oxidized lipids and proteins, and ROS, which is insulin resistant and causes dementia." (PMID 36497027, 2022). "We consider this approach a valid strategy as a preventative treatment for dementia and AD, especially for individuals who are obese and/or insulin-resistant/diabetic and therefore at high risk of developing cognitive dysfunction later in life." (PMID 35761012, 2022). "Evidence of insulin insensitivity triggering neuronal death has been identified as a major mechanism underlying dementia associated with IR." (PMID 37786742, 2022). "Poor insulin activity in the brain is linked with a high level of cholinergic action, leading to the development of dementia." (PMID 36497027, 2022). "In a randomized controlled trial, we investigated the effects of daily blueberry supplementation in a middle-aged sample of insulin-resistant participants with elevated risk for future dementia." (PMID 35458181, 2022). "Previous studies have reported that a higher risk of dementia was associated with increased insulin levels and HOMA-IR index." (PMID 36498726, 2022). "A prospective open-cohort study using the Swedish Dementia Registry and four Swedish registers/databases found that insulin use was associated with worsening Mini-Mental State Examination (MMSE) scores in both dementia incident and prevalent users." (PMID 35742986, 2022). "Brain insulin deficits and hyperinsulinemia are known to lead to memory loss and the development of dementia." (PMID 35765060, 2022). "At present, it is an emerging concern since anti-diabetic Food and Drug Administration approved insulin-sensitive drugs are showing positive effects on dementia risk factors via blocking TXNIP expression downstream associated with inflammatory signaling." (PMID 33803178, 2021).
dementia (continued). "This was based on the results of several studies that proved the association between impaired insulin signaling and the development of dementia in AD, in addition to evidence of suppressed brain insulin receptors and signaling in AD patients." (PMID 34366841, 2021). "Alzheimer’s Disease (AD), the leading cause of dementia, involves genetic, environmental and metabolic factors, including alterations in brain insulin signaling and glucose metabolism, which occur several years before the clinical symptoms become evident." (PMID 34830036, 2021). "For example, insulin therapy has been associated with anincreased risk of developing dementia, whereas thiazolidinedione exposure isassociated with protective effects and reduces the risk of dementia." (PMID 33907811, 2021). "Two follow-up studies have shown that low-insulin plasma levels during fasting were higher risk predictors for dementia and AD as compared to high insulin levels, and this association was independent of preclinical T2DM." (PMID 34065168, 2021). "Here, we emphasize that LCN2 has crucial pathogenic roles in dementia through the regulation of iron homeostasis, neuroinflammation, and insulin resistance." (PMID 33945675, 2021). "Epidemiological data validation confirms that insulin-resistant patients are prone to AD-associated dementia and that antidiabetic medication was effective in reducing or reversing risk factors in AD." (PMID 33803178, 2021). "Using intranasal insulin or using intravenous insulin under well-controlled conditions ensures a tight glycemic control which shows a promising effect in reducing the risk of developing dementia." (PMID 32190448, 2020). "In this study, we found that individuals who received insulin injections or oral hypoglycemic medications had a higher risk of dementia incidence." (PMID 33213100, 2020). "A study shows that there is a 50% increase in dementia risk in patients using peripheral insulin, which they attribute to the hypoglycemic effect of insulin." (PMID 32190448, 2020). "Given recent interest in the relationship between insulin and AD, it is noteworthy that patients in that study receiving exogenous insulin therapy were at the highest risk (RR 4.3) of developing dementia." (PMID 32992566, 2020). "In line with our findings, a recent case-control study demonstrated a positive association between insulin use and dementia risk." (PMID 30768625, 2019). "2DG is a competitive inhibitor of glucose not metabolized by hexokinase and, whenever the cause is, any impairment of the glycolysis results in neurodegeneration, brain insulin resistance, memory loss, and dementia." (PMID 31614723, 2019). "Our findings raise concern regarding increased dementia risk among middle-aged and old-adults who use insulin." (PMID 30768625, 2019). "Lastly, individuals from the participating cohorts are predominantly of European ancestry, yet it should be noted that ARIC study, which includes ~25% African-Americans, drives much of the association between insulin use and incident dementia." (PMID 30768625, 2019). "The nose-to-brain delivery of insulin is a promising strategy for preventing memory loss, however its therapeutic potential is limited to the early stage of dementia." (PMID 30518944, 2018). "Similar to preclinical studies, clinical studies show that disturbed insulin metabolism is a risk factor for cognitive dysfunction, brain atrophy, and dementia." (PMID 29743868, 2018). "The low tertile of insulin displayed excess risk for dementia (hazard ratio [HR] 2.34, 95% confidence interval [CI] 1.52–3.58) compared to the medium tertile, but the high tertile of insulin did not (HR 1.28, 95% CI 0.81–2.03)." (PMID 29997193, 2018). "A previous study reported a U-shaped association between fasting insulin and dementia in a 5-year follow-up of elderly men." (PMID 29997193, 2018).
dementia (continued). "Disruption of brain insulin signaling is one of the explanations for the consistently higher risk of AD and dementia in type 2 diabetic elderly." (PMID 30383799, 2018). "In this subsample, low insulin predicted dementia (HR 3.01, 95% CI 1.56–5.84) compared to the medium insulin tertile independently of higher APOE ε4 allele frequency (HR 2.18, 95% CI 1.29–3.67) per allele (data available from Dryad, right column)." (PMID 29997193, 2018). "The two extremes of fasting insulin levels (lower and upper 15th percentiles) increase the risk of dementia in a longitudinal study performed in Japanese-American elderly men." (PMID 29743868, 2018). "The purpose of this study was to investigate the association between fasting insulin and dementia in a female population followed over 34 years." (PMID 29997193, 2018). "Secondary outcomes will include body mass index, body composition, fasting blood lipids, C-reactive protein, fasting plasma glucose, fasting serum insulin, erythrocyte fatty acids, cognitive function, psychological health and well-being, and dementia risk." (PMID 29273039, 2017). "Defective insulin signaling is associated with decreased cognitive ability and development of dementia." (PMID 24349472, 2013). "This situation seems to be caused by peripheral insulin resistance, which is associated with increased risk of cognitive decline and dementia." (PMID 22389813, 2011). "Fourth, although eGDR provides a more practical and feasible alternative to the gold standard technique, future studies should compare the effects of eGDR with clamp-measured insulin sensitivity in dementia risk prediction to further clarify its biological significance." (PMID 41181882, 2026). "Impaired insulin signalling in the brain has been strongly associated with AD and other dementias." (PMID 40210453, 2025). "The role of these drugs in modulating dementia risk highlights the importance of glycaemic control in patients with cardiometabolic disorders, suggesting that interventions improving insulin sensitivity might bring cognitive benefits." (PMID 40818936, 2025). "Insulin treatment has also been associated with greater dementia severity." (PMID 41146261, 2025). "Past reviews have indicated insulin to be associated with an increased risk of dementia." (PMID 40017057, 2025). "Conversely, however, insulin administered intravenously and subcutaneously may raise the risk of dementia." (PMID 41226780, 2025). "Therefore, the association between insulin therapy and dementia risk should be cautiously interpreted." (PMID 39434474, 2024). "In recent years, it has been reported that metformin crosses the BBB and, given its insulin-sensitising properties, could play a role in improving brain IR and reducing the risk of dementia." (PMID 39200352, 2024). "Among antidiabetic medications, insulin therapy was linked to an increased risk of dementia." (PMID 39434474, 2024). "These investigations started with the Rotterdam Study, a large population-based study in the elderly, which revealed a positive association between DM and dementia (odds ratio: 1.3); pointing out that this association was strong in insulin-treated DM (odds ratio: 3.2)." (PMID 38003671, 2023). "Indeed, several studies demonstrated that the risk of dementia was highest in insulin-treated diabetic people." (PMID 37511061, 2023). "We investigated whether metformin was associated with reduced risk of dementia and whether this association was mediated predominantly by mechanisms other than improved glucose control or insulin use." (PMID 37878309, 2023). "Thus, TLR4 activation by AGE or HMGB1 can increase the risk of dementia trough promoting brain-insulin resistance." (PMID 37373216, 2023). "The findings of this study suggest that metformin cessation is associated with increased dementia incidence and that mechanisms other than glucose control or insulin use may mediate this association." (PMID 37878309, 2023).
dementia (continued). "Insulin, however, has been shown to increase the risk and incidence of dementia." (PMID 38152822, 2023). "It has been revealed that cardiovascular risk factors, changes in insulin metabolism, glucose toxicity and inflammation may be associated with dementia." (PMID 37582737, 2023). "Mediation models with HbA1c level and insulin usage 1 and 5 years after termination tested whether changes in blood glucose or insulin usage explained associations between early termination of metformin and dementia incidence." (PMID 37878309, 2023). "It was determined that there was an increased risk of developing dementia for insulin users." (PMID 38152822, 2023). "All these pathologies share several common clinical and biochemical manifestations, such as chronic inflammation, alterations in insulin signaling and insulin resistance, and altered energy metabolism, which contribute to a significant decline in cognitive function with a high risk of dementia." (PMID 35615716, 2022). "The decline in neuronal ATP, possibly due to mitochondrial dysfunction and insensitivity of neurons to insulin, has been pinpointed as one of the mechanisms contributing to the onset of neurodegeneration and associated pathological conditions including dementia." (PMID 37786742, 2022). "The authors also noted that the risk of dementia is significantly increased by various other DM indicators like high 2-hour post-prandial blood sugar levels, high HbA1c levels, and low and high levels of fasting plasma insulin." (PMID 35164844, 2022). "On the contrary, another study revealed that caffeine may be associated with a reduced dementia and AD risk, since caffeine can interact with and affect several other mechanisms, including elevated insulin sensitivity and antioxidant capacity." (PMID 36430879, 2022). "In addition, hyperinsulinemia due to insulin resistance was reported to increase the risk of dementia by causing the accumulation of beta-amyloid, which competitively binds to insulin to decompose enzymes and hyperphosphorylate tau proteins." (PMID 35742517, 2022). "Importantly, epidemiologic studies point long-term hyperinsulinemia as a risk factor for dementia, while insulin administration to AD patients improves memory formation, by keeping glucose levels in the brain constant." (PMID 35406040, 2022). "Although the increased inflammation associated with these diseases interacts with dementia through complex mechanisms, the relationship between increased inflammation and the perturbed insulin/insulin-like growth factor (IGF)-1 signaling pathway in the brain is consistent." (PMID 35892598, 2022). "Due to the important role of insulin signaling pathway in the regulation of brain functions, the development of brain insulin resistance seems to be highly implicated in the promotion of AD-like dementia in DS, representing a key pathological event." (PMID 33670211, 2021). "Mechanistic studies suggest that T2DM may be linked with dementia through cardiovascular risk factors such as alterations in glucose, insulin, and amyloid metabolism." (PMID 33868373, 2021). "Subcutaneous and intravenous insulin can increase the risk of dementia." (PMID 32190448, 2020). "A previous animal study showed that sitagliptin may increase the risk of dementia by aggravating tau phosphorylation and insulin resistance in the brain." (PMID 32121372, 2020). "Some experts had put forward some hypothesis that insulin resistance, inflammation, accumulation of advanced glycation end products (AGEs), and oxidative stress may be associated with an increased risk of dementia in the T2DM population." (PMID 33134394, 2020). "Nevertheless, the association of insulin use with dementia risk in the total sample remained robust even after excluding individuals who are in their early phases of the disease (not treated with medications), and after adjusting for measures of glycemic control and eGFR." (PMID 30768625, 2019).
dementia (continued). "After adjusting for potential confounders including indices of glycemic control, insulin use was associated with increased risk of new-onset dementia (pooled HR (95% CI) = 1.58 (1.18, 2.12);p = 0.002) and with a greater decline in global cognitive function (β = -0.014±0.007;p = 0.045)." (PMID 30768625, 2019). "When participants with <20 years of follow-up were excluded in sensitivity analyses, the associations between variables describing insulin and glucose metabolism and dementia outcomes were strengthened (data available from Dryad, doi.org/10.5061/dryad.21v1r72)." (PMID 29997193, 2018). "Modifications in brain insulin metabolism are thought to be among the pathophysiological factors underlying dementia, whether due to AD or to vascular cognitive impairment and dementia (VCID)." (PMID 30383799, 2018). "Post hoc analyses based on quintiles showed increased risk of dementia for women in the fifth quintile (fasting insulin ≥17.8 mIU/L) compared to the fourth quintile (HR 2.48; 95% confidence interval [CI] 1.31–4.71; data available from Dryad, figure, doi.org/10.5061/dryad.21v1r72)." (PMID 29997193, 2018). "In addition, several studies have suggested that metabolic disorders associated with alterations of insulin homeostasis are risk factors for developing cognitive decline and even dementia." (PMID 30364261, 2018). "It is possible that the proportion of subjects with low insulin was relatively large compared to modern cohorts, which may have made it more likely to observe the association with dementia in the present sample." (PMID 29997193, 2018). "In the case of leptin, as compared to adiponectin, the opposite direction of correlations with the same parameters were stated in all-cause dementia i.e. positive correlation with BMI, fasting glucose, insulin, HOMA-IR, IL-6 and hsCRP and positive correlation with HDL-C." (PMID 28421328, 2017). "However, the molecular mechanisms underlying the connection between insulin resistance and dementia are far from understood." (PMID 26658276, 2015). "Our present findings provide important experimental evidence supporting that intranasal insulin treatment might be used for preventing anesthesia-induced risk for memory loss and dementia." (PMID 24910612, 2014). "In the Rotterdam Study, diabetic patients treated with insulin were at highest risk of dementia." (PMID 24489845, 2014). "Many authors have suggested that insulin alterations and changes in glucose metabolism may condition the risk of developing dementia." (PMID 25346723, 2014). "This point was discussed also by L. Moll and M. Schubert that reviewed the literature dealing with the role of insulin and insulin-like growth factor-1 in the pathogenesis of obesity-associated dementia, with focus on the possible contribution of forkhead-box transcription factors (FoxO)." (PMID 22761616, 2012). "Insulin use was related to higher risk of dementia in two studies." (PMID 19127292, 2009). "Impaired insulin metabolism may cause neuronal damage; thus, it will be a risk factor of dementia." (PMID 40076944, 2025). "Among the dietary patterns in cases (MCI and dementia individuals) where the consumption of “pastries and cookies” was positively associated with insulin levels, eating sugar-filled pastries or candies can cause blood glucose levels to rise, leading the pancreas to produce the hormone insulin." (PMID 39166127, 2024). "However, in our study the beneficial effects of insulin degludec and liraglutide, both associated with a reduced risk of dementia in frail, older adults with T2DM, may have been blunted in non-responders, potentially due to dysbiosis and/or drug resistance." (PMID 37008061, 2023). "The main motivation for this study came from the observation of a U-shaped risk curve for fasting serum insulin and incident dementia in adults, which suggested that different genetic variants may be associated with the tails of the insulin spectrum and the various phenotypes of dementia." (PMID 37420130, 2023).